CAMKK2 (calcium/calmodulin dependent protein kinase kinase 2)
Diseases named in the same sentence as CAMKK2 in open-access papers (continued):
Sharing a sentence is not in itself a finding about the gene and the disease.
pulmonary fibrosis (1 paper, 2025). Chronic progressive interstitial lung disorder characterized by the replacement of the lung tissue by connective tissue, leading to progressive dyspnea, respiratory failure, or right heart failure. "RESULTS: This study revealed that CAMKK2 expression was significantly downregulated in pulmonary fibrosis, concomitant with impaired mitochondrial function-related proteins (PGC-1α, MFN1and MFN2)." (PMID 41053564, 2025). "In vivo studies showed that AAV-mediated CAMKK2 delivery significantly attenuated bleomycin-induced pulmonary fibrosis in mice." (PMID 41053564, 2025). "Therefore, targeting CAMKK2 presents a novel and promising therapeutic strategy for the treatment of pulmonary fibrosis." (PMID 41053564, 2025). "CONCLUSIONS: In summary, these findings collectively demonstrate that CAMKK2 regulated mitochondrial dynamics and OXPHOS function via AMPK/PGC-1α signaling pathway to alleviate pulmonary fibrosis in lung fibroblasts." (PMID 41053564, 2025).
Sepsis (1 paper, 2023). Sepsis is defined as life-threatening organ dysfunction caused by a dysregulated host response to infection. "Hence, in LPS-induced systemic inflammation (and even sepsis), whether J147 can regulate mitochondrial function, affect microglial polarization, and activate the CAMKK2/AMPK/mTOR pathway, thereby alleviating organ dysfunction in sepsis, warrants further exploration." (PMID 37676534, 2023).
triple-negative breast carcinoma (1 paper, 2025). An invasive breast carcinoma which is negative for expression of estrogen receptor (ER), progesterone receptor (PR), and human epidermal growth factor receptor 2 (HER2). "Ligand-directed degraders of CAMKK2 have also been developed and shown to impair migratory capacity and metastatic potential of triple negative breast cancer cells." (PMID 40945690, 2025).
vulvar cancer (1 paper, 2024). "EP4 and CaMKK2 are known to correlate with the progression and survival rates in cancers such as vulvar cancer and breast cancer." (PMID 38745046, 2024).
cancer (60 papers, 2014 to 2025). A tumor composed of atypical neoplastic, often pleomorphic cells that invade other tissues. "CaMKK2 has a significant impact on various physiological processes related to energy and glucose metabolism, inflammation, and cancer, by influencing signaling cascades and the pathogenesis of metabolic diseases." (PMID 39998213, 2025). "We highlight the potential of targeting the stiffness‐sensitive CaMKK2 pathway as a promising strategy to reduce immunosuppression for cancer therapy and regulate the immune response in wound healing." (PMID 40036145, 2025). "CAMKK2 is a kinase that regulates actin assembly to guide cell adhesion, migration, and morphogenesis during tissue homeostasis and cancer metastasis." (PMID 39373517, 2024). "Here, we review the structure, regulation, and function of CaMKK2 and discuss its potential as a treatment target for neurological disorders, metabolic disease, and cancer." (PMID 39268917, 2024). "CaMKK2 is known to be significantly overexpressed in many cancers, including prostate, glioblastoma, liver and ovarian cancer." (PMID 36815702, 2023). "Given the significant literature on the role of AMPK and CAMKIV activities on metabolic regulation, and their established status as CaMKK2 substrates, many of the biological effects of CaMKK2 on cancer have been attributed to this relationship." (PMID 36815702, 2023). "Future direction: Translational research studies will be important to identify sub-types of cancers that are dependent on CaMKK2 and COPI trafficking." (PMID 36815702, 2023). "Our recent study suggests that there are fundamental roles for CaMKK2 as a regulator of membrane trafficking that can have equally profound effects on the metabolic and hence the proliferative capacity of cancer cells." (PMID 36815702, 2023). "First, we are yet to functionally link the CAMKK2-mediated changes in circulating insulin levels to the observed changes in cancer cell size, mTOR signaling, and cancer progression." (PMID 35741020, 2022). "Next, we castrated mice to determine if CAMKK2 status would impact cancer progression in TRAMP mice under conditions that mimic ADT." (PMID 35741020, 2022). "Molecular knockdown or genetic knockout of CAMKK2 in human xenograft models of CRPC confirmed CAMKK2’s cancer cell-autonomous roles in vivo." (PMID 35741020, 2022). "Together, these data force us to reevaluate the potential mechanisms of action from prior data reporting anti-cancer effects in models leveraging systemic CAMKK2 inhibition via either germline genetic alterations (ex." (PMID 35741020, 2022). "In so doing, it suggests that CAMKK2 regulates the capacity of the secretory pathway and lysosomal function with implications for biologically informed combination treatments and cancer subtype selection." (PMID 34725334, 2021). "CaMKK2 exists in major internal organs, tissue and cells, involved in energy balance, glucose tolerance, inflammation, cancer and so on." (PMID 34693860, 2021). "This suggests that CAMKK2 supports cancer cell proliferation by maintaining the membrane trafficking capacity of cells, including lysosomal acidification and activity." (PMID 34725334, 2021). "It is therefore important to determine which biological processes are affected by CAMKK2 to explain its role in promoting the proliferation of cancer cells." (PMID 34725334, 2021). "In aggregate, these findings, in conjunction with the ability of CaMKK2 to regulate the NRF2 signaling and in turn ferroptosis in cancer cells, pinpoint Nrf2 as a potential relevant downstream target of CaMKK2 in MDSC." (PMID 34712241, 2021). "In particular, CAMKK2 activation has been shown to contribute to cell death resistance and cell survival in the context of cancer." (PMID 34943872, 2021). "There is therefore an interesting inverse relationship between the effect of GEMIN4 and CAMKK2 on cancer cell proliferation, as well as in the impact of androgen on their expression." (PMID 34725334, 2021).
cancer (continued). "Decreasing CAMKK2 activity using pharmacological inhibition, or the depletion of CAMKK2 using small interfering RNA (siRNA), reduces cell proliferation, migration and invasion in several cancer types." (PMID 31941153, 2020). "In cancer cell lines, CAMKK2 activates AMPK, altering cell metabolism and promoting cell proliferation." (PMID 31941153, 2020). "This is only the second paper to link DAPK activity with the negative regulation of CaMKK2 via phosphorylation at Ser511, and the only one involving cancer cells." (PMID 29914450, 2018). "CaMKK2, on the other hand, is overexpressed in a number of cancers, including castrate-resistant prostate cancer." (PMID 29914450, 2018). "Two predominant upstream kinases are known to activate AMPK: liver kinase B1 (LKB1), a tumor suppressor, and calcium-calmodulin kinase kinase-2 (CaMKK2), a tumor promotor over-expressed in many cancers." (PMID 29914450, 2018). "Here we report the functional effects of nine rare-variant point mutations that were detected in large-scale human genetic studies and cancer tissues, all of which occur close to two regulatory phosphorylation sites and the catalytic site on human CaMKK2." (PMID 28230171, 2017). "CaMKK2 controls insulin signaling, metabolic homeostasis, inflammation and cancer cell growth highlighting its potential as a therapeutic target for a variety of diseases." (PMID 28924233, 2017). "GGH silencing could also activate AMPK through LKB1 and CAMKK2 phosphorylation in various cancer cell lines and normal lung cells." (PMID 40268350, 2025). "Nevertheless, CaMKK2 has emerged as a pivotal decoder of Ca2+-signals in multiple tissues, and a key regulator of brain function and energy metabolism, with pathophysiological relevance for neurological disorders, metabolic diseases, and cancer." (PMID 39268917, 2024). "Pan-cancer analysis showed that CAMKK2 was significantly overexpressed in ICC." (PMID 38082327, 2023). "In addition, CAMKK2/AMPK research has primarily concentrated on cancer, while I/R research has mainly focused on myocardial I/R therapy." (PMID 37132110, 2023). "CAMKK2-regulated differences in cancer cell size and mTOR signaling (assessed by p-S6 IHC) combined with the sustained alterations in circulating insulin levels suggest that insulin mediates CAMKK2’s effects on cancer via control of systemic metabolism." (PMID 35741020, 2022). "Beyond CAMKK2’s role in cancer, CAMKK2 regulates several other physiological conditions that could indirectly contribute to cancer progression." (PMID 35741020, 2022). "Cancer cell size and mTOR signaling was diminished in tumors propagated in Camkk2-null mice." (PMID 35741020, 2022). "Calcium/calmodulin-dependent kinase kinase 2 (CAMKK2) belongs to the subfamily of calcium/calmodulin-dependent protein kinase and is involved in the maintenance of energy balance, adiposity, glucose homeostasis, inflammation, and cancer." (PMID 36606188, 2022). "We suggest that SOC channels and CAMKK2 may constitute novel drug targets for potentiating the anti-cancer effect of ATRA in APL patients." (PMID 34943872, 2021). "CaMKK2 is an important component of multiple signalling pathways that regulate glucose metabolism, adipogenesis, nutrient intake, inflammation and bone homoeostasis and has been shown to be deregulated in a number of diseases, such as obesity and cancer." (PMID 34725334, 2021). "A few researches are concerned with the correlation of miRNAs and CaMKK2 in cancer." (PMID 34693860, 2021). "CaMKK2 is found to be expressed in both cancer cells and within stromal cells (, S1A)." (PMID 31164648, 2019). "To date, most studies of CaMKK2 in cancer have focused on its cancer cell intrinsic activities." (PMID 31164648, 2019). "Calcium/calmodulin-dependent kinase kinase 2 (CaMKK2) is highly expressed in several cancers." (PMID 31164648, 2019). "These activities of CaMKK2 within myeloid cells suggested to us that it may also impact tumor biology in a cancer cell extrinsic manner." (PMID 31164648, 2019).
cancer (continued). "CAMKK2 was reported to be exclusively expressed in the myeloid lineage and participates in the regulation of several relevant physiological and pathophysiological processes, including hematopoiesis, cancer, inflammation, and immune responses." (PMID 29979707, 2018). "It has been reported that CaMKK2 plays an important role in neuron development, adipogenesis and cancer progression, however, its function in skeletal muscle differentiation and regeneration remains unknown." (PMID 27783047, 2016). "These effectors include the Ca2+-calmodulin dependent protein kinase kinase-2 (CaMKK2) enzyme, which is the core component of a signaling cascade that plays a key role in important physiological and pathophysiological processes, including brain function and cancer." (PMID 39268917, 2024). "Thus, CaMKK2 may contribute to tumor pathobiology through both cancer cell intrinsic and extrinsic actions." (PMID 31164648, 2019). "In particular, the AMPK/MTOR and the canonical AMPK/PI3K/AKT/MTOR cascades were more highlighted in luminal B cancers (by CAMKK2 and MTOR) and in HER2-enriched cancers (by CAMKK2, PIK3R4 and MTOR), respectively." (PMID 40700427, 2025). "Collectively, our study uncovers that CaMKK2 and ATR-CHK1 target STN1 to enable its fork protective function, and suggests an important role of STN1 phosphorylation in cancer development." (PMID 38036565, 2023). "Histological analyses revealed that cancer cells were smaller in the TRAMP;Camkk2−/− mice compared to TRAMP;Camkk2+/+ controls." (PMID 35741020, 2022). "We found MTOR and CAMKK2 as a feature important to both Luminal B and HER2-enriched cancers, while PIK3R4, a regulatory subunit of PI3K complex, was observed to be significant to TNBC and HER2-enriched cancers within the autophagy module." (PMID 40700427, 2025). "In summary, our study reaffirms the significance of CALML6 and the EP4/CALML6/CaMKK2/AMPK signaling pathway in OSCC progression, offering a comprehensive overview of their roles in cancer cell migration and suggesting them as potential targets for OSCC therapy." (PMID 38745046, 2024). "Given the lack of effective treatments for this highly aggressive cancer subtype, it suggests that the use of CAMKK2 inhibitors, which are currently in development, warrants further investigation for the treatment of NEPC." (PMID 35741020, 2022). "The CaMKK2/β/AMPK cascade plays important roles in the regulation of the energy metabolism and metabolic processes; this role is the same in cancer cell proliferation." (PMID 36232320, 2022). "Interestingly, while both LKB1 and CaMKK2 are involved in activating AMPK, their effects on cancer appear to be quite different." (PMID 29914450, 2018).
tumor (55 papers, 2013 to 2025). "In functional studies, CaMKK2 deletion prevented M2‐like/pro‐tumoral polarization caused by matrix stiffening, which in turn hindered tumor growth." (PMID 40036145, 2025). "CAMKK2 helps cells endure a nutrient-deficient tumor microenvironment, which indicates that CAMKK2 is necessary for PCa growth in vivo." (PMID 36769263, 2023). "CaMKK2 is highly expressed in pro-tumor cells and is associated with worsened survival in patients with GBM." (PMID 36309495, 2022). "This indicates that hematopoietic CaMKK2 deficiency is sufficient to promote these anti-tumor TIL phenotypes." (PMID 36309495, 2022). "In summary, we found that CaMKK2 deficiency dramatically remodels the immune TME to a more anti-tumor, ICB-responsive phenotype, and away from phenotypes associated with ICB resistance." (PMID 36309495, 2022). "The results indicated that deletion of CaMKK2 in the host attenuated the growth of engrafted tumor cells, and this phenomenon was associated with increased antitumor T cell response and decreased accumulation of MDSC." (PMID 34712241, 2021). "The results from these studies indicated that deletion of CaMKK2 in the host attenuated the growth of engrafted tumor cells, and this phenomenon was associated with increased antitumor T cells response and decreased accumulation of MDSCs." (PMID 34712241, 2021). "Flow cytometry analysis confirmed this result and showed robust Camkk2-reporter activity in tumor-associated CD11b+ myeloid cells, but minimal activity in CD11b- non-myeloid cells." (PMID 34712241, 2021). "Analysis of the tumor-associated myeloid cell repertoire revealed that CD11b+ MHC II+ cells accumulated preferentially in tumors from Camkk2−/− mice." (PMID 31164648, 2019). "Tumor-associated macrophages (TAMs) isolated from Camkk2−/− mice expressed higher levels of chemokines involved in the recruitment of effector T cells compared to WT." (PMID 31164648, 2019). "Here the authors investigate the role of CaMKK2 expression in the tumour microenvironment and show that CaMKK2 expression in tumour-associated macrophages promotes tumour growth by suppressing T cell anti-tumour activity." (PMID 31164648, 2019). "CaMKK2 is overexpressed in multiple tumor types and associated with disease progression." (PMID 40725182, 2025). "The increased abundance of IFNγ secreting CD4+ TILs in CaMKK2-deficient mice, in addition to chemotactic signals from DC-like TAMs (Cxcl9, Cxcl10), may explain the enhanced tumor penetrance seen by CD4+ and myeloid cells in the setting of CaMKK2 deficiency." (PMID 36309495, 2022). "In addition, there was no significant reduction in myeloid infiltration per mm3 of the tumor in the setting of CaMKK2 deficiency, and there was instead a higher percentage of myeloid cells found intratumorally, rather than peritumorally." (PMID 36309495, 2022). "Indeed, as with CD8+ T cells, CD4+ T cells were critical for the anti-tumor effect mediated by CaMKK2 deficiency." (PMID 36309495, 2022). "High expression levels of CAMKK2 were previously reported in TAMs and activation of this kinase was shown to support tumor growth." (PMID 41255709, 2025). "In breast cancer, calcium-dependent kinases such as CaMKK2 are expressed in both cancer cells and stromal cells, contributing to tumor growth and immune-suppressive status in the tumor microenvironment." (PMID 40433361, 2025). "CaMKK2 selectively regulates stiffness‐induced macrophage polarization, impacting tumor growth and wound healing." (PMID 40036145, 2025). "On the other hand, such an effect was negligible when tumor cells were co‐cultured with Camkk2−/− BMDMs." (PMID 40036145, 2025). "Specifically, CSNK2A1/3 was identified as highly ranking in the P0422-T1 tumor line and the kinases CAMKK2 and PIP4K2C were identified in the P0119-T1 CAF line." (PMID 39221276, 2024).